DDX5 (DEAD-box helicase 5)
Diseases named in the same sentence as DDX5 in open-access papers (continued):
Sharing a sentence is not in itself a finding about the gene and the disease.
cancer (continued). "DDX5 has been implicated in cancer development and progression by functioning in several key cancer cell activities, such as proliferation, migration, cytoskeletal reorganization, and the epithelial-mesenchymal transition (EMT)." (PMID 31032220, 2019). "DDX5, a transcriptional co-activator of several cancer-associated transcription factors, promoted cancer cell proliferation and metastasis." (PMID 29540201, 2018). "DDX5 was found to be involved in several biological functions as transcriptional coactivator and to be associated with cancer progression, and it has also been demonstrated to have important roles in RNA metabolism, including miRNA processing and transcription." (PMID 38689093, 2024). "This procedure plausibly explained that the cancer-suppressive effect caused by AURKAIP1 knockdown could be effectively rescued by overexpression of both DDX5 and β-catenin respectively." (PMID 38040691, 2023). "Consistently, decreased DDX5 expression is associated with R-loops accumulation in cancer cells." (PMID 37596619, 2023). "However, these two experiments also show that DDX5 expression levels that are too high or too low will increase the risk of cancer migration and lesions." (PMID 35992805, 2022). "CRC is the fourth most deadly cancer worldwide, where DDX5 is often mutated and/or overexpressed." (PMID 32817263, 2020). "This tripartite mechanism parallels recent findings in cancer biology, where DDX5 collaborates with METTL3 to regulate m6A-dependent RNA splicing, but represents the first report of such a pathway in viral latency." (PMID 41218081, 2025). "Aberrant expression and functional alterations of DDX5 have been reported in multiple cancers, including RMS, where its overexpression is associated with enhanced tumor growth and cancer cell proliferation." (PMID 40950397, 2025). "DDX5, for example, is upregulated in many cancers, including CRC, and plays a master role in transcription factor activation and RNA metabolism." (PMID 40940954, 2025). "DDX3, DDX5, and DHX9 are among the DEAD/H‐box helicases which have been most closely linked to cancer." (PMID 39620586, 2025). "It is generally accepted that DDX5 contributes to cancer cell proliferation by facilitating RNA metabolism and enhancing activity of growth-promoting transcription factors by functioning as a transcriptional coactivator." (PMID 40869977, 2025). "Among the identified gene targets, DEAD-box helicase 5 (DDX5) emerged as a key gene of interest due to its known involvement in cancer-related pathways." (PMID 41303368, 2025). "The expression of DDX5 is up-regulated in various types of cancers, and its functional involvement in processes for the malignant transformation of tumors, such as invasion and metastasis, has been demonstrated." (PMID 38612503, 2024). "Taken together, these findings suggest that MA likely exerts its anticancer effects by inhibiting the expression of the key oncogenic factor DDX5 and then inducing apoptosis in cancer cells." (PMID 39494326, 2024). "Overall, DDX5 has been found to be involved in cancer progression through either tumor-suppressive or oncogenic mechanisms, depending on its interaction partners, even in the same cancer type." (PMID 38689093, 2024). "The DEAD-box RNA helicase family plays important roles in cancer development and tumor metabolism, of which DDX5 is the most representative member." (PMID 39494326, 2024). "In this regard, various studies have indicated the miRNA regulation-mediated roles of DDX5 in cancer." (PMID 38689093, 2024). "As a multifunctional protein influencing diverse biological behaviors, DDX5 holds important potential as a cancer biomarker or therapeutic target." (PMID 39193132, 2024). "Remarkably, the deficiency of DDX5 in hepatocytes activates the interconnected Wnt/β-catenin-NIK/p52/RelB- and NRF2 pathways, all relevant to cancer." (PMID 39122708, 2024).
cancer (continued). "DDX5 is over-expressed in a variety of cancers and is thought to contribute to the growth of cancer cells by enhancing the activity of growth-promoting transcription factors, such as c-Myc and β-catenin, and by facilitating RNA metabolism." (PMID 39769018, 2024). "In our view in either case, this further indicates that targeting DDX5 for cancer treatment would have low toxicity to normal tissues including ISCs." (PMID 37596619, 2023). "Such unique features make DDX5 an intriguing therapeutic target for the treatment of human cancers, with limited low toxicity to normal tissues." (PMID 37596619, 2023). "This is because cancer cell apoptosis and malignant transformation can represent the two possible outcomes of a single process regulated by DDX5, reflecting different intensity of DNA damage." (PMID 37596619, 2023). "DDX5 expression was decreased under hypoxia in cell lines (cancer and normal), tumor xenografts and hypoxic tumors from cancer patients leading to reduced R‐loop accumulation and replication stress." (PMID 37013907, 2023). "This evidence starkly demonstrates that DDX5 knockdown escalates the expression of genes promoting cancer progression while suppressing those maintaining cell homeostasis and tumor suppression." (PMID 38136426, 2023). "Based on the updated publications in the literature reviewed above, we can conclude that DDX5 is involved in promoting the reprogramming of the metabolism of glucose, lipid, and nucleotide in cancer." (PMID 37596619, 2023). "There are several review articles that have focused on DDX5 (p68) as a cancer target and biomarker involved in tumorigenesis and cancer development for cancer therapy." (PMID 37596619, 2023). "As the most studied protein of the DEAD box family of RNA helicases, DDX5 (DEAD-box helicase 5) has been confirmed to extensively participated in regulating multiple aspects of cancer development and progression." (PMID 38040691, 2023). "Recent new publications further support the notion that DDX5 is a critical biomarker and target in specialized rare cancers." (PMID 37596619, 2023). "Here, we review this specialized new area to extend the vision on DDX5’s role and augment the potential of cancer therapeutics using DDX5 as a biomarker and target." (PMID 37596619, 2023). "For instance, increased production of DDX5 and DDX17 has been linked to tumorigenesis in certain types of cancer, while MBNL1 isoforms have been found to differently affect cancer cell viability and migration." (PMID 37882878, 2023). "A recent study has focused on the function of DDX5 in regulating cellular life cycles, cancer and development, and spermatogenesis." (PMID 37007947, 2023). "We should point out that DDX5 is involved in glucose metabolism would impact on human disease treatment including, but not limited to cancer." (PMID 37596619, 2023). "Still, the authors concluded that the oncogenic role of DDX5, at least in part, manifests as upregulation of respiration, supporting the energy demands of cancer cells." (PMID 37596619, 2023). "In this section, we will focus on recent key publications relevant to DDX5 acting as a biomarker and target for cancer therapeutics." (PMID 37596619, 2023). "These unique characteristics of DDX5 make DDX5 a particularly interesting target for the treatment of cancer and potentially, for other diseases as well." (PMID 37596619, 2023). "One of the aspects of DDX5 that intrigued us was the finding that is overexpressed or amplified in a wide range of cancers." (PMID 37013907, 2023). "DDX5 has emerged as a critical regulator in resolving DNA transcription-replication-coupled R-loop formation resolution to prevent cancer cell death as a result of DNA double-strand breaks (DSBs)." (PMID 37596619, 2023). "DDX5 is an upstream master regulator in cancer and positively controls the expression of survivin, Mcl-1, XIAP, and cIAP2." (PMID 36771042, 2023).
cancer (continued). "The multifaceted DNA repair function of DDX5 in cancer can explain the inconsistency with other studies which have identified DDX5 as a biomarker of cancer progression and a therapeutic target for cancer treatment." (PMID 37596619, 2023). "The findings revealed that the expression of DDX5 mRNA increased in only a small fraction of the 33 cancer types in TCGA." (PMID 36313454, 2022). "The results demonstrated that the expression of DDX5 mRNA was associated with the infiltration of B cells, CD8+ T cells, and cancer-associated fibroblasts in several cancer types." (PMID 36313454, 2022). "In this study, the association between the expression of DEAD-box helicase 5 (DDX5) and the incidence of various cancers was determined using the R software and other web datasets." (PMID 36313454, 2022). "DDX3X and DDX5 have been shown to operate in these pathways as well, with either positive or negative regulatory roles depending on the cancer type." (PMID 35954483, 2022). "Analysis of the relationship between the expression levels of DDX5 mRNA and tumor progression revealed that the prognosis worsened following the increased expression of DDX5 mRNA in various cancer types." (PMID 36313454, 2022). "This is very important because the studies documented in the current literature demonstrated that DDX5 is a superior oncogenic biomarker and target for targeted cancer therapy." (PMID 35604033, 2022). "DDX5 normally functions by performing as a transcriptional co-activator of several transcription factors and has been shown to motivate tumorigenesis and cancer progression." (PMID 35510394, 2022). "The results indicated that the levels of DDX5 protein were significantly elevated in eight different cancer types." (PMID 36313454, 2022). "The aberrant regulation of DDX5 expression possibly plays a significant role in the genesis of cancer." (PMID 36313454, 2022). "The cancer tissues were categorized into two groups based on the expression of DDX5 mRNA, namely, the high and low expression groups, based on TCGA data." (PMID 36313454, 2022). "The results obtained herein can aid in elucidating the role of DDX5 in carcinogenesis, and suggest that DDX5 can serve as a potential biomarker in several cancer types." (PMID 36313454, 2022). "The results demonstrated that DDX5 mRNA was differentially expressed between tumor and matched normal tissues in 27 different cancer types, with the exception of the malignancies for which data pertaining to matched normal tissues were absent." (PMID 36313454, 2022). "The results of correlation analysis between the pan-cancer methylation and expression of DDX5 have been depicted with a lollipop graph (p < 0.001)." (PMID 36313454, 2022). "We observed that of the 33 tumor types in TCGA, the expression of DDX5 mRNA was significantly reduced in 17 cancer types but significantly increased in eight tumor types." (PMID 36313454, 2022). "Overall, the abnormal expression of DDX5 in many types of cancer and its regulation support an important role of this protein in promoting cancer cell proliferation." (PMID 35954483, 2022). "Analysis of the methylation levels of the DDX5 gene promoter using the UALCAN dataset revealed the potential function of DDX5 across all cancer types." (PMID 36313454, 2022). "The significance of the functions of DDX5 in the prognosis of cancer and tumor immunity require further investigation in future studies." (PMID 36313454, 2022). "Of the 32 types of tumors in TCGA, 26 cancer types showed various degrees of alterations in the DDX5 gene." (PMID 36313454, 2022). "DDX5 (also called p68) is overexpressed in many types of cancer and holds great promise in molecular diagnostics, prognostics and targeted therapy." (PMID 35604033, 2022). "DEAD-box RNA helicase DDX5 (DDX5) can participate in transcription factor activation to function in cancer occurrence and progression." (PMID 35014946, 2022).
cancer (continued). "The roles of two well-characterized members of this family, DDX3X and DDX5, as both oncogenes and oncosuppressors have been documented in several cancer types." (PMID 35954483, 2022). "The expression of DDX5 mRNA was highly correlated with the infiltration of CD8+ T cells, cancer-associated fibroblasts, and B cells in a wide variety of malignancies." (PMID 36313454, 2022). "It is necessary to explore the mechanism of action of DDX5/DDX17 in cancer to provide a solid theoretical basis for the application of DDX5/DDX17 in cancer diagnosis and treatment." (PMID 35992805, 2022). "DDX5 stimulates ribosome biogenesis and increases protein production, consistent with the higher metabolic rate required by cancer cells during tumorigenesis." (PMID 35992805, 2022). "The available data on DDX5 indicated that it acts much more often as an oncogene, but it can also have tumor suppressor functions in specific cancer types." (PMID 35954483, 2022). "We therefore assessed the expression of DDX5 in 33 cancer types using data from TCGA, CPTAC, and GEO databases, with various webtools and bioinformatics software." (PMID 36313454, 2022). "Three survival indicators, namely, OS, PFI, and DSS, indicated a poor prognosis with upregulated mRNA expression of DDX5 in these two cancers." (PMID 36313454, 2022). "Recently, supinoxin (RX-5902), a small-molecule inhibitor of DDX5, has been developed for cancer therapy and is currently in clinical trials with metastatic triple-negative breast cancer patients." (PMID 35992805, 2022). "Despite extensive reports elucidating the role of DDX5 in promoting cancer progression, little is known about its function during HCC pathogenesis." (PMID 33764710, 2021). "To explore the regulatory mechanism through which miR-519b-3p affected CRC progression, we used TargetScan to predict miR-519b-3p target genes and identified DDX5 as a potential target, because of its proto-oncogenic role in human cancers 16-18." (PMID 34234865, 2021). "DDX5 also participates in ribosome biogenesis, cell proliferation, tumorigenesis, and cancer development." (PMID 33623715, 2021). "As a component of RNA helicase, DDX5 acts as a transcriptional co-regulator with multiple transcription factors during the promotion of cancer cell proliferation." (PMID 33764710, 2021). "The AKT pathway is activated abnormally in several types of cancers with increased expression of DDX-5 and is closely related to cancer progression." (PMID 34320120, 2021). "DEAD-box helicase 5 (DDX5) greatly contributes to cancer development and facilitation of viral propagation." (PMID 33909701, 2021). "DDX5 is aberrantly expressed/modified in several types of cancers, suggesting that it plays important roles in cancer development and progression." (PMID 33807895, 2021). "DDX5 is frequently overexpressed in many cancers and contributes to disease pathogenesis and progression." (PMID 33764710, 2021). "The expression of DDX5 is elevated in numerous cancer types and as such represents a valid cancer therapeutic target." (PMID 33015627, 2020). "Herein, we show DDX5 downregulation imparts cancer stem cell properties to hepatocytes, including hepatosphere formation, resistance to sorafenib and cisplatin, expression of pluripotency genes, and activation of Wnt signaling." (PMID 33042264, 2020). "Knockdown of DDX5 inhibited the proliferation of cancer cells in vitro and the growth of xenografts in immunodeficient hosts." (PMID 32817263, 2020). "In human cancer cell lines, DDX5 interacts with β-catenin protein and the long non-coding RNA NEAT1 to promote oncogene expression." (PMID 32817263, 2020).
cancer (continued). "As expect, the results of western blotting assay shown that the OGT, DDX5, and O‐GlcNAcylation levels were significantly increased in all cancer cell lines compared to that in the NCM460 cell line." (PMID 30484950, 2019). "The multitasking transcriptional regulators DDX5 and DDX17 included in our dataset contain an helicase domain in their structure reported to be associated with cancer development and cell proliferation." (PMID 30971948, 2019). "As an oncogene, DDX5 is overexpressed in a variety of tumors and contributes to promoting cancer cell proliferation and metastasis." (PMID 29540201, 2018). "The DEAD-box RNA helicase 5 (DDX5), an ATP-dependent DEAD-box RNA helicase, acts as a transcriptional co-activator of several cancer-associated transcription factors and plays an important role in transcription initiation." (PMID 29540201, 2018). "Increasing evidence suggests that DDX5 participates in carcinogenesis and cancer progression via promoting cell proliferation and metastasis." (PMID 28216662, 2017). "As one of the resveratrol-binding proteins, the RNA helicase DDX5/p68 was reported to be overexpressed and amplified in several malignant tumors and have oncogenic properties, we focused on the role of DDX5 as a target of resveratrol in cancer inhibition." (PMID 27148684, 2016). "Resveratrol directly bound to and promoted metalloprotease-dependent degradation of DDX5 protein, leading to cancer cell death with inhibition of the mTORC1 pathway." (PMID 27148684, 2016). "The fact that of the 10 rarely mutated genes, 5 (BCL2L1, CDC42, DDX5, AKT1 and APC) are listed in cancer gene databases indicates such association-based selection is useful." (PMID 27808240, 2016). "The oncogenic role of Ddx5 in cell proliferation and cancer and the role of NF-κB as one of the identified Ddx5 interactors have been proved." (PMID 25925689, 2015). "DDX5 was highly differentially expressed in LUAD and associated with three cancer types according to the Cox model." (PMID 26202601, 2015). "It is generally regarded that DDX5 promotes tumorigenesis by functioning as a transcriptional coactivator for growth-promoting transcription factors, thereby contributing to proliferation of cancer cells." (PMID 40869977, 2025). "For instance, DDX5 is crucial for the processing of RNA, influencing various aspects of mRNA splicing and ribosome biogenesis, which are essential for rapid protein synthesis in fast-growing cancer cells." (PMID 40090465, 2025). "DDX5, in contrast, is generally described to have a consistently oncogenic effect through its regulation of the Wnt, Notch, mammalian target of rapamycin (mTOR), and forkhead box O3a (FOXO3a) pathways all involved in cancer progression." (PMID 39620586, 2025). "Therefore, targeted inhibition of DDX5 can switch cancer cells from undergoing growth arrest to apoptosis and cell death." (PMID 39494326, 2024). "DDX5 appears to utilize distinct signaling cascades via interactions with unique proteins in different types of tissues/cells to elicit opposing roles (e.g., smooth muscle cells versus cancer cells)." (PMID 37596619, 2023). "This is a very interesting area for DDX5 to regulate cancer metabolism." (PMID 37596619, 2023). "Since the inhibition of DDX5 does not induce smooth muscle cell loss; instead, increasing their proliferation and survival, this effect can additionally benefit cancer patients." (PMID 37596619, 2023). "This could be resulted from a low DDX5 (protein)-induced feedback that promotes the synthesis of DDX5 mRNA in tumors (for cell survival), and low DDX5 (protein) in tumor cells may facilitate the infiltration of cancer killing immune cells into TME." (PMID 37596619, 2023). "Additionally, studies indicated that degradation of DDX5 (protein) by FL118 induces cancer cell apoptosis but at the same time induces DDX5 mRNA levels." (PMID 37596619, 2023).